LYPD2 (LY6/PLAUR domain containing 2)
Synonyms: LYPDC2; RGTR430; UNQ430
Tractability: Antibody: UniProt places it where antibodies can reach, with high confidence; its Gene Ontology location is reachable by antibodies, with high confidence; UniProt predicts a signal peptide or a membrane-spanning region.
Gene: Protein-coding gene on chromosome 8 (142,750,150 to 142,752,532, reverse strand). Ensembl gene ENSG00000197353.
Subcellular location: Cell membrane
Pathways (Reactome):
Metabolism of proteins: Post-translational modification: synthesis of GPI-anchored proteins
Gene Ontology:
Molecular function: protein binding
Cellular component: extracellular region; plasma membrane
Genetic constraint (gnomAD): Loss-of-function variants: 6 observed, 8.14 expected, observed/expected ratio (o/e) 0.74, 90% interval 0.4 to 1.44. That is too few expected variants to judge how well the gene tolerates losing a copy. Missense variants: 177 observed, 154.37 expected, observed/expected ratio (o/e) 1.15, 90% interval 1.01 to 1.3. Synonymous variants: 78 observed, 72.4 expected, observed/expected ratio (o/e) 1.08, 90% interval 0.9 to 1.3.
Homologues: Orthologues: chimpanzee LYPD2 (97% identical), macaque LYPD2 (93% identical), pig LYPD2 (74% identical), rat Lypd2 (70% identical), mouse Lypd2 (67% identical), dog LYPD2 (66% identical). Paralogues in human: SLURP1 (34% identical), LYPD1 (30% identical), CD59 (28% identical).
Diseases named in the same sentence as LYPD2 in open-access papers:
LYPD2 is named in the same sentence as 9 diseases in open-access papers, as found by Europe PMC text mining. Sharing a sentence is not in itself a finding about the gene and the disease. The quoted sentences say what the papers report.
cervical cancer (2 papers, 2017 to 2022). A primary or metastatic malignant neoplasm involving the cervix. "The function of LYPD2 is currently unknown, but expression has been shown to be higher in cervical cancer tissue compared to surrounding normal tissues, supporting the idea that LYPD2 is an HPV-regulated host gene." (PMID 35632695, 2022). "Moreover, hypermethylation of LYPD2 and SHE were associated with poor overall survival (OS); hypermethylation of FGF8 and HSPA6 were associated with poor progression free survival (PFS) in patients with cervical cancer." (PMID 29029430, 2017).
asthma (1 paper, 2025). "We identified 8 key genes (LOC100132287, CEACAM5, PRR4, CPA3, POSTN, LYPD2, TCN1, and SCGB3A1) associated with asthma by combining the LASSO regression model and the SVM-RFE method." (PMID 39963184, 2025). "LYPD2 and C7orf26 were also lowly expressed in patients with asthma in GSE158752 dataset." (PMID 39963184, 2025). "However, the gene LYPD2 had high AUC values, indicating that it has good predictive efficacy, which requires further exploration of the relationship with asthma." (PMID 39963184, 2025). "LOC100132287, LYPD2, SCGB3A1 and C7orf26 (Chromosome 7 open reading frame 26) had low expression in asthma patients." (PMID 39963184, 2025).
head and neck cancer (1 paper, 2019). A primary or metastatic malignant neoplasm affecting the head and neck. "LYPD2:LYPD2 RNA is expressed at high levels compared to adjacent normal tissues in cervical and head and neck cancer are associated with a favorable prognosis as shown by the human protein atlas." (PMID 31068932, 2019).
keratoconus (1 paper, 2020). A degenerative, structural disorder of the eye, characterized by a cone-shaped protrusion of the cornea. "In addition, a combination of genes significantly upregulated in the KJ samples only, S100A8, S100A9, ADAMTS14, LYPD2 and AOC1 may yield distinguishing biomarkers for subtypes of keratoconus." (PMID 32555404, 2020).
mastitis (1 paper, 2024). Inflammation of breast tissue during lactation or postpartum due to an obstructed duct or infection. "Among them, cnvr_137 contains genes such as LY6D, LYNX1, LYPD2, SLURP1,THEM6, PSCA, TSNARE1, and ARC associated to clinical mastitis in US Holstein dairy cows." (PMID 38771855, 2024).
infection (1 paper, 2025). The state of being infected such as from the introduction of a foreign agent such as serum, vaccine, antigenic substance or organism. "Among the top 10 enriched genes identified for each infection condition, LYPD2 was also identified in all four screens." (PMID 40901862, 2025).
tumor (1 paper, 2025). "We analyzed the data from TCGA and found that LYPD2 expression was not significantly different between tumor and normal tissues in patients with GC, and that LYPD2 expression was not correlated with clinical stage or prognosis." (PMID 40953331, 2025).
LYPD2 also shares sentences with these, for which no sentence is quoted: cancer (1 paper); diabetes (1).